PRKD1 (protein kinase D1)
Description:
Serine/threonine-protein kinase that converts transient diacylglycerol (DAG) signals into prolonged physiological effects downstream of PKC, and is involved in the regulation of MAPK8/JNK1 and Ras signaling, Golgi membrane integrity and trafficking, cell survival through NF-kappa-B activation, cell migration, cell differentiation by mediating HDAC7 nuclear export, cell proliferation via MAPK1/3 (ERK1/2) signaling, and plays a role in cardiac hypertrophy, VEGFA-induced angiogenesis, genotoxic-induced apoptosis and flagellin-stimulated inflammatory response. Phosphorylates the epidermal growth factor receptor (EGFR) on dual threonine residues, which leads to the suppression of epidermal growth factor (EGF)-induced MAPK8/JNK1 activation and subsequent JUN phosphorylation. Phosphorylates RIN1, inducing RIN1 binding to 14-3-3 proteins YWHAB, YWHAE and YWHAZ and increased competition with RAF1 for binding to GTP-bound form of Ras proteins (NRAS, HRAS and KRAS). Acts downstream of the heterotrimeric G protein beta/gamma-subunit complex to maintain the structural integrity of the Golgi membranes, and is required for protein transport along the secretory pathway. In the trans-Golgi network (TGN), regulates the fission of transport vesicles that are on their way to the plasma membrane. May act by activating the lipid kinase phosphatidylinositol 4-kinase beta (PI4KB) at the TGN for the local synthesis of phosphorylated inositol lipids, which induces a sequential production of DAG, phosphatidic acid (PA) and lyso-PA (LPA) that are necessary for membrane fission and generation of specific transport carriers to the cell surface. Under oxidative stress, is phosphorylated at Tyr-463 via SRC-ABL1 and contributes to cell survival by activating IKK complex and subsequent nuclear translocation and activation of NFKB1. Involved in cell migration by regulating integrin alpha-5/beta-3 recycling and promoting its recruitment in newly forming focal adhesion. In osteoblast differentiation, mediates the bone morphogenetic protein 2 (BMP2)-induced nuclear export of HDAC7, which results in the inhibition of HDAC7 transcriptional repression of RUNX2. In neurons, plays an important role in neuronal polarity by regulating the biogenesis of TGN-derived dendritic vesicles, and is involved in the maintenance of dendritic arborization and Golgi structure in hippocampal cells. May potentiate mitogenesis induced by the neuropeptide bombesin or vasopressin by mediating an increase in the duration of MAPK1/3 (ERK1/2) signaling, which leads to accumulation of immediate-early gene products including FOS that stimulate cell cycle progression. Plays an important role in the proliferative response induced by low calcium in keratinocytes, through sustained activation of MAPK1/3 (ERK1/2) pathway. Downstream of novel PKC signaling, plays a role in cardiac hypertrophy by phosphorylating HDAC5, which in turn triggers XPO1/CRM1-dependent nuclear export of HDAC5, MEF2A transcriptional activation and induction of downstream target genes that promote myocyte hypertrophy and pathological cardiac remodeling. Mediates cardiac troponin I (TNNI3) phosphorylation at the PKA sites, which results in reduced myofilament calcium sensitivity, and accelerated crossbridge cycling kinetics. The PRKD1-HDAC5 pathway is also involved in angiogenesis by mediating VEGFA-induced specific subset of gene expression, cell migration, and tube formation. In response to VEGFA, is necessary and required for HDAC7 phosphorylation which induces HDAC7 nuclear export and endothelial cell proliferation and migration. During apoptosis induced by cytarabine and other genotoxic agents, PRKD1 is cleaved by caspase-3 at Asp-378, resulting in activation of its kinase function and increased sensitivity of cells to the cytotoxic effects of genotoxic agents. In epithelial cells, is required for transducing flagellin-stimulated inflammatory responses by binding and phosphorylating TLR5, which contributes to MAPK14/p38 activation and production of inflammatory cytokines. Acts as an activator of NLRP3 inflammasome assembly by mediating phosphorylation of NLRP3 (By similarity). May play a role in inflammatory response by mediating activation of NF-kappa-B. May be involved in pain transmission by directly modulating TRPV1 receptor. Plays a role in activated KRAS-mediated stabilization of ZNF304 in colorectal cancer (CRC) cells. Regulates nuclear translocation of transcription factor TFEB in macrophages upon live S.enterica infection (By similarity). Acts as a regulator of social behavior by mediating phosphorylation of OXTR, enhancing G(q)-dependent G protein-coupled receptor signaling.
Synonyms: PKD; PKD1; PRKCM; PKCM; PKC-mu; CHDED
Tractability: Small molecule: an approved drug acts on it; a high-quality ligand is known; it belongs to a druggable protein family. Antibody: UniProt places it where antibodies can reach, with high confidence; its Gene Ontology location is reachable by antibodies, with high confidence; the Human Protein Atlas places it where antibodies can reach. PROTAC: ubiquitination databases record sites on it; a small molecule that binds it is known.
Target class: Kinase; Protein Kinase; Enzyme; CAMK protein kinase group; CAMK protein kinase PKD family
Chemical probes: CID755673
Gene: Protein-coding gene on chromosome 14 (29,576,479 to 30,191,898, reverse strand). Ensembl gene ENSG00000184304.
Subcellular location: Cytoplasm; Cell membrane; Golgi apparatus, trans-Golgi network
Subcellular location (Human Protein Atlas): Plasma membrane; Cytosol
Pathways (Reactome):
Metabolism: Sphingolipid de novo biosynthesis
Gene Ontology:
Molecular function: diacylglycerol-dependent serine/threonine kinase activity; identical protein binding; kinase activity; phosphatidylinositol 3-kinase activator activity; protein binding; protein serine kinase activity; protein serine/threonine kinase activity; diacylglycerol-dependent, calcium-independent serine/threonine kinase activity; ATP binding; heat shock protein binding; protein kinase activity; protein kinase C binding
Biological process: cellular response to amino acid starvation; cellular response to hydroperoxide; cellular response to oxidative stress; cellular response to vascular endothelial growth factor stimulus; Golgi organization; intracellular signal transduction; positive regulation of angiogenesis; positive regulation of autophagy; positive regulation of blood vessel endothelial cell migration; positive regulation of canonical NF-kappaB signal transduction; positive regulation of endothelial cell chemotaxis; positive regulation of endothelial cell migration; positive regulation of endothelial cell proliferation; positive regulation of neuron projection development; positive regulation of phosphatidylinositol 3-kinase/protein kinase B signal transduction; positive regulation of phospholipase C-activating G protein-coupled receptor signaling pathway; positive regulation of transcription by RNA polymerase II; protein autophosphorylation; transepithelial transport; vascular endothelial growth factor receptor signaling pathway; Golgi vesicle transport; integrin-mediated signaling pathway; negative regulation of endocytosis; phospholipase C-activating G protein-coupled receptor signaling pathway; positive regulation of NLRP3 inflammasome complex assembly; and 18 more
Cellular component: autophagosome membrane; cytosol; Golgi apparatus; plasma membrane; trans-Golgi network; cell cortex; cell-cell junction; cytoplasm; membrane; nucleus; perinuclear region of cytoplasm; Z disc
Genetic constraint (gnomAD): Loss-of-function variants: 48 observed, 80.07 expected, observed/expected ratio (o/e) 0.6, 90% interval 0.47 to 0.76. The upper end of that interval is the gene's LOEUF score, 0.76, which puts it in group 3 of 6, group 1 being the genes least tolerant of losing a copy. Missense variants: 994 observed, 1,081.6 expected, observed/expected ratio (o/e) 0.92, 90% interval 0.87 to 0.97. Synonymous variants: 410 observed, 398.7 expected, observed/expected ratio (o/e) 1.03, 90% interval 0.95 to 1.12.
Gene-disease validity (ClinGen):
ClinGen rates the evidence that PRKD1 causes each of these diseases.
congenital heart disease (autosomal dominant; autosomal recessive): Limited. A heart disease that is present at birth.
Homologues: Orthologues: macaque PRKD1 (99% identical), pig PRKD1 (96% identical), chimpanzee PRKD1 (94% identical), rat Prkd1 (94% identical), mouse Prkd1 (93% identical), guinea pig PRKD1 (88% identical), rabbit PRKD1 (87% identical), zebrafish prkd1 (80% identical), tropical clawed frog prkd1 (79% identical), Drosophila melanogaster PKD (51% identical), Caenorhabditis elegans dkf-2 (49% identical), Caenorhabditis elegans dkf-1 (35% identical). Paralogues in human: PRKD3 (69% identical), PRKD2 (67% identical).
Diseases named in the same sentence as PRKD1 in open-access papers:
PRKD1 is named in the same sentence as 135 diseases in open-access papers, as found by Europe PMC text mining. Sharing a sentence is not in itself a finding about the gene and the disease. The quoted sentences say what the papers report.
breast carcinoma (33 papers, 2009 to 2025). "We found that lymph node invasion (p=0.0000009), high pathological size (p=0.002), high histological grade (p=0.03) and high PRKD1 expression (p=0.003) were significantly associated with a poorer prognosis in the whole breast cancer population." (PMID 29796183, 2018). "We found that high PRKD1 mRNA levels were significantly and independently associated with a low metastasis-free survival in the whole breast cancer population and in the triple-negative breast cancer (TNBC) subtype specifically." (PMID 29796183, 2018). "Recent studies have identified missense mutations in the coding sequence of the PRKD1 gene in human colorectal and breast cancers." (PMID 23971832, 2013). "Hypermethylation of the PRKD1 promoter in breast cancer cell lines directly correlated with a loss of PRKD1 gene expression." (PMID 23971832, 2013). "In summary, our analysis of patient data indicates that decrease or loss of PKD1 expression in human breast cancer is due to hypermethylation of the PRKD1 promoter." (PMID 23971832, 2013). "Methylation of the PRKD1 promoter has been linked to silencing seen in breast cancer tumor progression, and targeted upregulation of PRKD1 has been suggested as an approach to reduce breast cancer invasiveness." (PMID 38002248, 2023). "By comparing normal and tumor patient tissue as well as normal, noninvasive, and highly invasive breast cancer cell lines, we show that PRKD1 gene promoter methylation directly correlates with the loss of PKD1 expression and the invasive potential of breast tumors or cells." (PMID 23971832, 2013). "As a serin/threonine kinase expressed in normal breast cells, the PRKD1 gene has been proved to be a key protein to inhibit the invasive phenotype in breast cancer." (PMID 38472894, 2024). "In 2009, Eiseler and colleagues identified that the PRKD1 promoter was aberrantly methylated in highly invasive breast cancer cell lines, leading to a decrease in the protein expression." (PMID 37293129, 2023). "PRKD1, a direct target of miR-34a, was capable of regulating cancer stemness in chemoresistant human breast cancer cells by altering GSK3/β-catenin signaling, and ectopic miR-34a expression reduced PRKD1 resulting in suppressed self-renewal of BCSCs." (PMID 33763422, 2021). "miR-34a suppresses tumorshphere formation, CSCs’ self-renewal ability, the expression of stem markers, and drug resistance in the MCF-7 breast cancer cell line by inhibiting serine/threonine-protein kinase D1 (PRKD1)." (PMID 31861404, 2019). "By targeting NOTCH 1 and protein kinase D1 (PRKD1), miR-34a modulates chemosensitivity of breast cancer cells to adriamycin, and stimulates breast cancer stemness and drug resistance, respectively." (PMID 31554373, 2019). "We show that lysophosphatidic acid/protein kinase D1 (LPA/PKD-1)-CD36 signaling is a bona fide breast cancer promoter via stimulating microvascular remodeling in chronic diet-induced obesity (DIO)." (PMID 28186980, 2017). "As seen in the case of breast cancer, the loss of PKD1 in gastric cancer occurs due to hypermethylation of the PRKD1 promoter." (PMID 26848698, 2016). "For example, in breast cancer and gastric cancer the loss of PKD1 has been shown to be mediated through hypermethylation of the PRKD1 promoter." (PMID 26848698, 2016). "In this study, we highlight the role of the serine/threonine-protein kinase D1 (PKD1) in ERα-positive breast cancers." (PMID 25287328, 2014). "Using these primers sets in MSP-PCR, we confirmed that DNA methylation of the PRKD1 promoter was present only in the highly invasive breast cancer cell lines, whereas it was unmethylated in the non- or minimally invasive cells." (PMID 23971832, 2013). "Herein we show that the gene promoter of PRKD1 is aberrantly methylated and silenced in its expression in invasive breast cancer cells and during breast tumor progression, increasing with the aggressiveness of tumors." (PMID 23971832, 2013).
breast carcinoma (continued). "We assessed the methylation status over a stretch of 32 CpG sites of the PRKD1 promoter by bisulfite sequencing in a subset of highly invasive and non- or minimally invasive breast cancer cell lines as well as in the “normal” MCF-10A cells." (PMID 23971832, 2013). "At present, a large number of PRKD1 gene related studies mainly focus on breast cancer." (PMID 38472894, 2024). "The discovery of the miR-34a/PRKD1 mechanism may contribute to the investigation of breast cancer and its CSCs on the molecular level." (PMID 31861404, 2019). "Therefore, the PRKD1 promoter is silenced in invasive breast cancer cells, leading to low expression of PRKD1, which contributes to tumor invasion and metastasis." (PMID 31861404, 2019). "Consequently, in breast cancer, the transition from a less aggressive to a metastatic phenotype is characterized by PRKD1 (PKD1) gene promoter methylation and downregulation of PKD1 expression." (PMID 30555634, 2018). "In breast cancer cells however, PRKD1 may display a dual function as an oncogene, stimulating drug resistance in breast cancer stemness or as a tumor suppressor, blocking invasion and metastasis." (PMID 29854292, 2018). "To further assess the role of PKD1 in human breast cancer, we evaluated by qRT-PCR, as described in ‘Materials and methods’, the expression of PRKD1 gene (encoding PKD1) in 7 non-cancerous breast epithelial cell lines and 31 breast cancer cell lines." (PMID 25287328, 2014). "So far, the only mutation in the PRKD1 gene found for breast cancer does not explain the loss of its expression, and it is conceivable that downregulation of PKD1 expression is due to epigenetic modifications such as DNA methylation of its promoter." (PMID 23971832, 2013). "The goal of this study was to determine if epigenetic silencing of PRKD1 occurs in invasive cancer and whether this can be a driver of breast cancer cell metastasis." (PMID 23971832, 2013). "MiR-34a inhibited the migration, invasion, and proliferation and modulated drug sensitivity in breast cancer cells by affecting antiapoptotic genes Bcl-2 and CCND1 and the Ras family proteins, NOTCH1 and PRKD1." (PMID 38919953, 2024). "We have previously shown that the Protein Kinase D1 (PKD1) can promote both proliferation and estrogen independence in breast cancer cells." (PMID 29796183, 2018). "Together, these results show that PRKD1, PRKD2 and PRKD3 are expressed in breast cancer and that PRKD1 mRNA expression is an independent prognostic factor in the entire BC population and in the TNBC subpopulation." (PMID 29796183, 2018). "We have previously reported that protein kinase D1 stimulates proliferation and oncogenic properties of estrogen-dependent MCF-7 breast cancer cells." (PMID 25287328, 2014). "Inhibition of WNT1 changes the phenotype of CD44+CD24−ALDH1 stem cells and reduces their ability to form tumours and cell migration, and suppression of GSK3/β-catenin signals by an inhibitor of protein kinase D1 (PRKD1) is sufficient to reduce the stem and chemoresistance of breast cancer cells." (PMID 35563449, 2022).